EFCAB5 (EF-hand calcium binding domain 5)
Synonyms: FLJ46247
Tractability: No criterion of Open Targets' tractability assessment is met for any kind of drug.
Gene: Protein-coding gene on chromosome 17 (29,929,200 to 30,108,452, forward strand). Ensembl gene ENSG00000176927.
Subcellular location (Human Protein Atlas): Nuclear bodies; Mitochondria
Gene Ontology:
Molecular function: calcium ion binding
Genetic constraint (gnomAD): Loss-of-function variants: 117 observed, 150.28 expected, observed/expected ratio (o/e) 0.78, 90% interval 0.67 to 0.91. The upper end of that interval is the gene's LOEUF score, 0.91, which puts it in group 3 of 6, group 1 being the genes least tolerant of losing a copy. Missense variants: 1,580 observed, 1,674.5 expected, observed/expected ratio (o/e) 0.94, 90% interval 0.9 to 0.98. Synonymous variants: 547 observed, 588.09 expected, observed/expected ratio (o/e) 0.93, 90% interval 0.87 to 1.
Homologues: Orthologues: chimpanzee EFCAB5 (98% identical), macaque EFCAB5 (94% identical), dog EFCAB5 (71% identical), pig EFCAB5 (70% identical), rat Efcab5 (61% identical), rabbit EFCAB5 (61% identical), mouse Efcab5 (54% identical), tropical clawed frog efcab5 (33% identical), Drosophila melanogaster CG15747 (3% identical), Caenorhabditis elegans ccdc-55 (3% identical). Paralogues in human: NSRP1 (6% identical).
Diseases named in the same sentence as EFCAB5 in open-access papers:
EFCAB5 is named in the same sentence as 3 diseases in open-access papers, as found by Europe PMC text mining. Sharing a sentence is not in itself a finding about the gene and the disease. The quoted sentences say what the papers report.
male infertility (1 paper, 2025). The inability of the male to effect fertilization of an ovum after a specified period of unprotected intercourse. "Our findings establish CFAP91 as an essential scaffolder of RS3 assembly and EFCAB5 as a sperm-specialized movement regulator, advancing understanding of axonemal specialization in mammalian spermatozoa and its relevance to male infertility." (PMID 40931011, 2025). "By using proximity labeling, this study uncovers EFCAB5 as a sperm-specific protein associated with CFAP91 in sperm tails, revealing its crucial role in regulating sperm motility and offering insights into the molecular basis of male infertility." (PMID 40931011, 2025).
memory impairment (1 paper, 2023). "Thus, we suggest that variants in EFCAB5 could affect memory impairment in T2D subjects." (PMID 37342358, 2023).
EFCAB5 also shares sentences with these, for which no sentence is quoted: Azoospermia (1 paper).